REG4 (regenerating family member 4)
Diseases named in the same sentence as REG4 in open-access papers (continued):
Sharing a sentence is not in itself a finding about the gene and the disease.
cancer (continued). "Moreover, REG4-positive cancer cells show more frequent resistance to chemoradiotherapy, especially 5-FU-based chemotherapy." (PMID 33489872, 2020). "The understanding of mechanisms of REG4 in many cancer types has increased in the recent years." (PMID 33489872, 2020). "The role and clinical significance of REG4 in human cancers." (PMID 33489872, 2020). "Furthermore, immunohistochemistry showed that REG4 expression was increased in benign tumors, borderline tumors and primary carcinoma compared to normal ovarian tissue." (PMID 26077911, 2015). "REG4 transcription is induced by the GLI1 transcription factor, which is activated by sonic hedgehog, regulates stem cell proliferation, and is associated with a poor cancer prognosis." (PMID 24533081, 2014). "Several reports in the literature suggest a major role for REG4 in cancer." (PMID 19834624, 2009). "Gene copy number gain of the reg4 gene was confirmed by qPCR in 14 cancer samples." (PMID 19834624, 2009). "Through RNA‐seq analysis, we have also shown differential expression of other cancer biomarkers by CHRDL2, such as EGR1, REG4 and TFF1, which have been shown to regulate proliferation, migration and metastasis." (PMID 40434957, 2025). "REG4 can interact with transmembrane CD44, G protein-coupled receptor 37, mannan and heparin on cancer cells." (PMID 36172286, 2022). "Transforming growth factor beta downregulated REG4 and ALDH1 expression, which is related to the decline in cancer-initiating cell population size and tumorigenicity." (PMID 35310914, 2022). "We then validated the recurrence of carcinoma precursor cell population in our biopsy slides by probing their specific marker genes SOX4 and REG4, which are involved in carcinogenesis." (PMID 35221332, 2022). "Except that, the probability of some differential expression genes, such as MUC2, CLCA1, REG4, and FGF3 can be used as prognostic biomarkers in NSCLC is worth exploring because they have been reported as a biomarkers in other cancers as well." (PMID 33927719, 2021). "The finding of downregulation of CTLA4 and REG4 by CAP and H2O2 can help establish the molecular mechanism of how CAP inhibits cancer cell growth." (PMID 32947888, 2020). "It seems likely that increased expression of REG4, and upstream factors such as hedgehog, plays a role in the biology of SSA/Ps and possibly their progression to cancer." (PMID 24533081, 2014). "Interestingly, weekly intraperitoneal administration of a monoclonal antibody to reg4 halved the size of tumors generated by Mia-PaCa2 cells, suggesting that the antibody interfered with a paracrine/autocrine mechanism involving reg4 and stimulating cancer progression." (PMID 19834624, 2009). "Moreover, regenerating gene family member 4 (REG4) released from PDAC cancer cells can promote macrophage polarization to M2, as well as orchestrate the TME to favor cancer growth and metastasis." (PMID 37444617, 2023). "The negative regulation of REG4 by GATA6 was reversed to be positive from normal to cancer, the positive regulation of CA9 by GATA6 in normal tissue disappeared in cancer and the negative regulation of STC1 by GATA6 in normal stage was also disappeared in cancer." (PMID 35421923, 2022). "MiR-363 downregulates REG4 via suppressing GATA6 and promotes cancer cells growth." (PMID 33489872, 2020). "A recent advancement in the research studies on CRC indicates cancer stem cell (CSC) plays a significant role in tumor development, progression, and metastasis, where a significant elevation of regenerating family member 4 (REG4) protein was noticed in the tumor samples of CRC patients." (PMID 39056802, 2024). "Performing ELISA-based assays in a larger cohorts would not only show whether REG4 and A1AT are good CAT biomarkers in CRC, including other cancer types in the cohort would also show whether REG4 and A1AT would be applicable as CAT biomarkers in other cancer types as well." (PMID 38066386, 2024).
tumor (50 papers, 2009 to 2025). "The REG4 antibody that we tested strongly stained tumor‐associated neutrophils, and the CYP24A1 antibody gave weak or no staining, leading to the exclusion of these markers." (PMID 39935174, 2025). "Aberrant expression of REG4 is associated with tumor growth, survival, adhesion but also resistance to apoptosis." (PMID 34006939, 2021). "Reg4 mean expression (r2 = 0.23, p = 0.026) and mean intensity (r2 = 0.21, p = 0.039) were both associated with larger tumor size." (PMID 33659040, 2021). "The diagnostic and prognostic roles of REG4 expression can differ according to the tumor type and researchers." (PMID 34577861, 2021). "REG4 overexpression is frequently associated with aggressive phenotypes, unfavorable clinical parameters such as advanced tumor and nodal status, and drug-resistance." (PMID 33489872, 2020). "Moreover, many of these genes are associated with stemness, such as MUC5B, as well as tumor biology, including REG4, LYZ, EREG, KRT23, and RAMP1, which were also identified in a previous CRC single-cell study." (PMID 39350339, 2024). "In tumor cells, REG4 expression is associated with cell growth, survival, and anti-apoptosis." (PMID 34577861, 2021). "Reg4 expression was associated with larger tumor size (r2 = 0.23, p = 0.026)." (PMID 33659040, 2021). "Although we didn’t observe an association between Reg4 expression and recurrence risk in this study, possibly due to limited number of samples, our results clearly demonstrated that the expression of Reg4 promotes tumor growth and chemoresistance." (PMID 33659040, 2021). "They express proteins like AGR2 to potentiate VEGF and FGF2 signaling, and REG4 to intensify tumor invasion." (PMID 41450739, 2025). "Current research primarily focused on the detection of Reg3A and Reg4 levels in serum and tumor tissues, with superior accuracy and sensitivity compared to the existing biomarkers, making them promising novel indicators for both diagnosis and prognosis." (PMID 39857608, 2024). "In our preliminary studies, the single-chain variable fragment (scFv) against Reg3A and Reg4, two of the most commonly overexpressed Reg proteins in tumors, have demonstrated significant anti-tumor effects." (PMID 39857608, 2024). "SERPINA1, ITLN1, and REG4 upregulation in primary tumor tissues was negatively correlated with distant metastasis, indicating a protective effect on prognosis in patients with CRC." (PMID 38083905, 2023). "Silencing significantly REG4 reduced proliferation and tumor growth, and arrested the cell cycle by regulating E2F targets and the G2/M checkpoint." (PMID 36172286, 2022). "Knockdown of REG4 induced innate immune activation and reduced tumor growth in the xenografts, indicating that REG4 is a beneficial target for PDAC therapy." (PMID 35742884, 2022). "Here, we demonstrate that AsPC1 cells express high level of REG4, and that inhibiting REG4 in AsPC1 cells, when xenografted in zebrafish, activates innate immune cells and strongly suppresses the tumor growth." (PMID 35742884, 2022). "In clear contrast, the tumor size of AsPC1 cells at 4 dpi was significantly reduced by REG4 siRNA compared with the control." (PMID 35742884, 2022). "The TMA was immunohistochemically stained for Reg4, CD44, and CD44ICD proteins and analyzed to identify associations with tumor characteristics, recurrence and overall survival." (PMID 33659040, 2021). "We immunohistochemically stained our TMA with three proteins integral to the Reg4 pathway: Reg4, CD44, and CD44ICD and looked into associations with clinical parameters of tumor aggression." (PMID 33659040, 2021). "The correlations between REG4 expression and amount of tumor stroma as well as the mucinous component were evaluated." (PMID 34577861, 2021). "As a secretory protein, REG4 shows two mucin-like and perinuclear patterns with immunohistochemical staining and promotes carcinogenesis in tumor cells via both autocrine and paracrine manners." (PMID 33489872, 2020).
tumor (continued). "More detailed examination of the REG4 staining pattern revealed the strongest staining inside and between the mucinous inclusions of goblet-like tumor cells." (PMID 26981633, 2016). "Tumor expression of REG4 was evaluated by immunohistochemistry in 840 consecutive surgically treated CRC patients at Helsinki University Central Hospital." (PMID 25295732, 2014). "Our aim was to investigate tumor REG4 expression in CRC patients and its coexpression with other intestinal markers." (PMID 25295732, 2014). "We observed an important reduction in tumor size and an increased sensitivity to gemcitabine treatment in mice given once a week anti-reg4 antibody." (PMID 19834624, 2009). "Exposure to reg4 antibody resulted in a significant decrease in intra-tumor levels of pAkt, Bcl-xL, Bcl-2, survivin and cyclin D1." (PMID 19834624, 2009). "This analysis uncovered 2 tumor-associated epithelial populations, including a tumor-specific stem-like (tSTM, cluster 0) state defined by OLFM4 and LGR5, and a tumor-specific deep crypt secretory (tDCS, cluster 10) state characterized by REG4 with limited MUC2." (PMID 41282138, 2025). "Focusing on CRC patients with high tumor purity from the TCGA database, we found a resistant oncogenic signature of immune evasion (including REG4, CTSE, MUC1, TFF2, LCN2) that inversely correlated with cytotoxicity and immune infiltration deconvolution scores (T- and NK-cells)." (PMID 39632825, 2024). "In the current study, we investigated whether protein expression of REG4, SPINK4 and alpha-1 antitrypsin (A1AT, encoded by SERPINA1) in the tumor associated with CAT in an independent cohort of CRC patients." (PMID 38066386, 2024). "Seven hub genes, REG4, S100A7, CLCA1, FABP4, RETNLB, SFRP2, and WNT10A, were all significantly associated with CC patient prognosis and differentially expressed in normal and tumor tissues." (PMID 36941538, 2023). "In addition, to elucidate the correlation between REG4 and stroma of tumor, the implication of HIF-1α expression was investigated." (PMID 34577861, 2021). "In our study, REG4 expression was significantly correlated with tumor location." (PMID 34577861, 2021). "Moreover, because REG4 can be correlated with inflammation, the correlation between REG4 and tumor-infiltrating lymphocytes was investigated." (PMID 34577861, 2021). "In addition, REG4 concentration was measured in a time series of serum samples to determine the correlation to tumor burden." (PMID 26981633, 2016). "REG4 protein expression in the same set of tumor samples was assessed with western blotting." (PMID 26981633, 2016). "In particular, monoclonal antibodies targeting REG4 or its receptor could hold promise as novel anti-tumor reagents." (PMID 26387746, 2015). "Moreover, in whole sections, REG4 expression appeared in some cases in normal epithelium, but was down-regulated in tumor cells." (PMID 25295732, 2014). "As REG4 associated strongly with tumor histology, we analyzed mucinous and non-mucinous CRC separately." (PMID 25295732, 2014). "REG4 expression in tumor cells was cytoplasmic and slightly granular." (PMID 25295732, 2014). "Treatment with the reg4 antibody decreased tumor development by about 50%." (PMID 19834624, 2009). "In addition, combining reg4 antibody treatment with gemcitabine resulted in further reduction of tumor volume." (PMID 19834624, 2009). "To investigate whether interfering with REG4 expression would affect tumor ability to evade immune system, we inactivated REG4 gene in type I MSS CRC immunotherapy-resistant PDO model with high REG4 expression using small guide RNA (sgRNA) pairs designed to delete the transcription start site." (PMID 39632825, 2024). "In addition, the correlation between REG4 expression and tumor stroma was investigated." (PMID 34577861, 2021). "Cluster 10 showed elevated REG4 and MUC2, characteristic of a tumor-specific deep crypt secretory (tDCS) identity." (PMID 41282138, 2025).
tumor (continued). "REG4 activates CREB1 by interacting with its receptor, EGFR, in tumour cells, resulting in increased SRGN expression." (PMID 38862740, 2024). "Further experiments showed that recombinant REG4 (rREG4) activated CREB1 and upregulated SRGN expression in tumour cells." (PMID 38862740, 2024). "On the other hand, regenerating islet-derived 4 (REG4) induces the degradation of ACC1 or the ACLY proteasome, while lymph node and distant metastasis, and the tumor-lymph node metastasis stage are negatively correlated with REG4 overexpression." (PMID 39103344, 2024). "In vitro studies have shown that Reg4 promotes migration and invasion of CRC tumor cells with reversal of this phenomenon upon treatment with anti-Reg4 antibody." (PMID 33659040, 2021). "The three proteins, CTLA4, REG4, and ABCC12, which were regulated by both CAP and H2O2 have been known to be involved in tumor cell growth or drug resistance." (PMID 32947888, 2020). "Proliferating tumor cells in early stage PDAC express REG1A, REG1B, REG3A, and REG4 and throughout PDAC development." (PMID 31696115, 2019). "Since knockdown of GATA6 resulted in a more significant inhibition of tumor growth than REG4 or LGR5 knockdown alone, we examined the effect of REG4 and LGR5 double knockdown on the tumorigenicity of HT29 cells." (PMID 26387746, 2015). "Our results regarding five pairs of REG4-positive primary tumors and their corresponding lymph-node metastases showed that of five lymph nodes, only two showed REG4 expression; this may imply that a REG4-negative subpopulation of tumor cells is more likely to metastasize than REG4-positive cells." (PMID 25295732, 2014). "Here, the tumor cells elevate expression of immune signaling MHC II molecules (CD74, HLA-DRB1, HLA-DPA1) and immune-regulating secretory proteins (REG4, AGR2, AGR3), with AGR2 and REG4 specifically upregulated in RCRC." (PMID 41450739, 2025). "Other novel genes up-regulated in tumor cells, like SLC2A1 and REG4, promote M2 polarization." (PMID 39256888, 2024). "In zebrafish xenografted embryos, downregulation of REG4 in PANC1 cells did not affect the tumor growth." (PMID 35742884, 2022). "Furthermore, we found while individual knockdown of either REG4 or LGR5 partially inhibited tumor cell growth in nude mice, the double REG4/LGR5 knockdown inhibited tumor growth to an extent similar to the GATA6 knockdown." (PMID 26387746, 2015). "In some of our whole-tissue sections tumor tissue stained negative for REG4, but the adjacent benign epithelium expressed REG4 strongly, apparently representing an inflammatory reaction against the tumor." (PMID 25295732, 2014). "Our observations on mice transgenic for human REG4 cDNA under the villin promoter that leads to global overexpression of REG4 in the intestinal mucosa did not induce increased tumor formation or mucosal hyperplasia (unpublished data)." (PMID 25295732, 2014). "Expression of REG4 and SPINK4 in the tumor may indicate a proinflammatory status of the tumor." (PMID 38066386, 2024). "In addition, REG4 expression was not correlated with PD-L1 expressions of tumor and immune cells (p = 0.259 and p = 0.227, respectively)." (PMID 34577861, 2021). "REG4 expression was not significantly correlated with tumor-infiltrating lymphocytes (p = 0.790)." (PMID 34577861, 2021). "Furthermore, REG4 was located exclusively on the apical surface of the tumor cells, while the stroma was negative." (PMID 26981633, 2016). "Based on tumor stroma and mucinous component subgroups, prognostic stratification of CRC with and without REG4 expression was attempted." (PMID 34577861, 2021). "In non-mucinous, CRC REG4 positivity was a sign of favorable prognosis (p = 0.019, log-rank test); 5-year DSS for patients with positive cytoplasmic REG4 tumor expression was 67.9% (95% CI 60.5–75.3) compared to 57.8% (95% CI 53.5–62.1) for those with no cytoplasmic expression." (PMID 25295732, 2014).
adenocarcinoma (6 papers, 2011 to 2023). A common cancer characterized by the presence of malignant glandular cells. "In the lung, REG4 was highly expressed in KRAS-mutant adenocarcinoma with thyroid transcription factor-1 (TTF-1) hypoexpression." (PMID 36172286, 2022).
infection (6 papers, 2012 to 2025). The state of being infected such as from the introduction of a foreign agent such as serum, vaccine, antigenic substance or organism. "After 1 day of PAO1 infection, mice were injected with recombinant Reg4 protein daily at a dose of 50 μg/kg of body weight." (PMID 38501823, 2024). "REG4 is involved in infection and inflammation by enhancing macrophage polarization to M2, via activation of epidermal growth factor receptor (EGFR)/Akt/cAMP-responsive element binding and the killing inflammatory Escherichia coli, and closely linked to tumorigenesis." (PMID 36172286, 2022). "In addition to changes in goblet cell abundance during infection, there was a decrease in Reg4, a marker for DCS cells from 6 DPI, shown by proteomics and qRT-PCR analyses." (PMID 30940698, 2019). "Here, we investigated whether Reg4 affects PAO1 infection by affecting bacterial motility." (PMID 38501823, 2024).
inflammation (1 paper, 2024). Aberrant reaction of the microcirculation characterized by movement of fluid and leukocytes from the blood into extravascular tissues. "In the LPS-induced lung inflammation model of mice, Reg4 mRNA level peaked at 6 hours and then gradually decreased in the lung after LPS treatment." (PMID 38501823, 2024). "Taken together, our study demonstrates that Reg4 may provide protection against P. aeruginosa-induced pulmonary inflammation and fibrosis via its antibacterial activity." (PMID 38501823, 2024). "In the P. aeruginosa PAO1-chronic infection model, Reg4 significantly inhibits the colonization of PAO1 in the lung and subsequently ameliorates pulmonary inflammation and fibrosis." (PMID 38501823, 2024).
REG4 also shares sentences with these, for which no sentence is quoted: mucinous adenocarcinoma (3 papers); ovarian mucinous carcinoma (3); colon (2); Crohn disease (2); dysplasia (2); bacteremia (1); benign tumors (1); carcinoma of the uterine cervix (1); cardiovascular disease (1); cervical cancer (1); cholangiocarcinoma (1); cholecystolithiasis (1); chronic cholecystitis (1); colorectal adenocarcinoma (1); cystadenoma (1); helminth infection (1); infective endocarditis (1); Insulin resistance (1); intestinal cancer (1); kidney (1); leukemia (1); lymph node disease (1); lymphoepithelioma (1); metastasis (1); metastatic carcinoma (1); metastatic prostate carcinoma (1); myelodysplastic syndrome (1); nasopharyngeal carcinoma (1); oesophageal cancer (1); osteoarthritis (1).
A further 9 diseases each share a sentence with REG4 in 1 paper.